SSTR5 (somatostatin receptor 5)
Diseases named in the same sentence as SSTR5 in open-access papers (continued):
Sharing a sentence is not in itself a finding about the gene and the disease.
tumor (continued). "Herein, we report a case where preoperative examination indicated a suspected tumor with low SSTR2 and SSTR5 expression, whereas postoperative pathological examination revealed strong SSTR expression." (PMID 39507000, 2024). "By contrast, the new SSA analog named pasireotide demonstrated a strong antiproliferative effect in these tumor cells, characterized by a high expression of SSTR2 and SSTR5." (PMID 39064468, 2024). "Here, we report a case in which preoperative examination indicated a potential tumor with low somatostatin receptor 2 (SSTR2) and SSTR5 expression, whereas postoperative pathological examination indicated strong SSTR expression." (PMID 39507000, 2024). "SST and SSTR1-5 are well expressed in HT29 cells derived from low grade differentiated tumor whereas cell obtained from high grade and undifferentiated colon cancer namely SW480 are devoid of SST and SSTR5." (PMID 38203605, 2023). "About 88% of tumours that secreted excess growth hormone exhibited strong immunostaining for SSTR 2 and all tumours displayed weak immunoreactivity for SSTR5." (PMID 37851558, 2023). "Considering all the models, a patient stratification based on the extrasellar growth of the tumor, sex, age and the expression of E-cadherin, GHRL, IN1-GHRL, DRD2, SSTR5 and PEBP1 is proposed, with accuracies that stand between 71 to 95%." (PMID 35643771, 2022). "Sparsely granulated tumours (SGST) differed from the other subtypes in expression of SSTR2A, SSTR3, SSTR5 and E‐cadherin and occurred more often in young." (PMID 33491286, 2021). "In this report, we show that AE enters tumor cells via two of the five somatostatin receptors: SSTR2 and SSTR5." (PMID 33990938, 2021). "Differences related to tumor grade were evident for SSTR1 (p = 0.036), SSTR2 (p = 0.009) and SSTR5 (p = 0.029), while differences for SSTR3 (p = 0.059) were non-significant." (PMID 34830858, 2021). "SSAs, by activating SSTR3 or SSTR5, modify the expression and function of COX-2 in colon cancer cells, inhibiting tumor cell proliferation." (PMID 32121432, 2020). "Although gonadotropinomas have been shown to express SSTR (mainly SSTR2 and SSTR5) and type 2 dopamine receptors (DR2), the results with SSAs and dopamine agonists (DAs) are discrete regarding tumor shrinkage." (PMID 32121432, 2020). "Comparing relative receptor expression intensities between the two tumor entities, CCCs showed significantly higher intensities of expression of SSTR1, SSTR2, SSTR5, and CXCR4 than HCCs." (PMID 29282035, 2017). "The monoclonal antibodies against SSTR1, SSTR2, SSTR3, SSTR5, and CXCR4 produced distinct immunostaining of the plasma membrane, but also of the cytoplasm of the HCC and CCC tumor cells." (PMID 29282035, 2017). "In this present study of 99 surgically resected PNETs, tumor characteristics, histopathology, and patient outcomes were studied to ultimately determine the significance of SSTR-2a and SSTR-5 as prognostic markers for survival." (PMID 26447992, 2015). "The IRS scores of the SSTR2A and 3 demonstrated an inverse significant interconnection with the grading of the neoplasms, whereas the IRS of the SSTR5 and of the CXCR4 presented a significant positive relation with the grading." (PMID 26259237, 2015). "This limited utility is because in tumours, among the five subtypes of SSTRs (SSTR1-SSTR5), radionuclide-labelled octreotide can only bind to SSTR2 and SSTR5." (PMID 24805918, 2014). "Thus, it is reasonable to speculate that a combined SSTR5-based tumor therapeutic approach including both somatostatin analog and other inhibiting technology of PDX-1 [for example, RNA interference control of PDX-1] would help improve the traditional treatment with somatostatin analogs." (PMID 25009500, 2014). "Reportedly, the cultured tumor cells IMR32 and CFPAC-1 highly express some SSTRs, with BON cells natively expressing high levels of SSTR1, SSTR2 and SSTR5." (PMID 21892324, 2008).
tumor (continued). "Specifically, SSTR5 activates the MEK-ERK, Jun N-terminal kinase (JNK) and p38 pathways to mediate proliferation arrest, and affects differentiation, apoptosis, anti-angiogenesis and tumor metabolism." (PMID 40134804, 2025). "SSTR1 was expressed in three (75%), SSTR3 in two (50%), SSTR4 in 0% and SSTR5 in 0% of the GLP-1R-negative tumours, compared to eleven (23%) (p = 0.055), fifteen (31%) (p = 0.589), 0% and three (6%) (p = 1.000) in GLP-1R-positive tumours, respectively." (PMID 37894845, 2023). "Expression of SSTR2a was detected in all tumor specimens, whereas SSTR5 expression was absent in four samples." (PMID 34674191, 2022). "It has earlier been demonstrated in a mouse tumor model that the endocytosed receptors are predominantly recycled, and that the de novo synthesis is low for SSTR1- SSTR4, whereas SSTR5 is the only receptor which is stored intracellularly and can rapidly be recruited." (PMID 34822040, 2021). "Similarly, the expression of SSTR5 at gene and protein levels is negligible in human primary NFPT cells and primary tumor tissues, respectively." (PMID 34205778, 2021). "In contrast to these reports, our in vitro data suggest that everolimus leads to downregulation of SSTR5 and exerts its impact on tumor growth irrespective of SSA exposure." (PMID 31237925, 2019). "In conclusion, the protein expression of SSTR2, but not of SSTR5, is a valuable indicator in predicting biochemical and tumor size response to short-term SSA treatment in acromegalic patients." (PMID 28396686, 2017). "A different picture emerged regarding SSTR5 and CXCR4 expression in tumor capillaries." (PMID 29282035, 2017). "On the contrary, Vt in the tumor was lower for 68Ga-DOTANOC than for the other two tracers, and although 68Ga-DOTANOC has higher affinity for SSTR2 than 68Ga-DOTATOC, it also has affinity for SSTR3 and SSTR5." (PMID 25369268, 2014). "The results of RT-PCR demonstrated that SSTR2 and SSTR5 mRNAs existed abundantly in all 5 tumor cell lines, except for a lack of SSTR5 in MOLT-4 cells." (PMID 21892324, 2008). "Tumours not expressing an abundance of SSTR-2 over SSTR-5 subtypes may have reduced response to these agents and may, in fact, experience preferential suppression of glucagon over insulin, leading to hypoglycaemia." (PMID 40697399, 2025). "Nevertheless it may be worth assessing expression of both SSTR2 and SSTR5, especially in the metastatic setting, regardless of the primary tumour status to evaluate response to SSAs and to better select patients for treatment." (PMID 36980746, 2023). "No changes in SSTR5 expression level was observed in the third tumor (#3)." (PMID 35626057, 2022). "Indeed, NT-3 cells may be a more suitable tumor cell model than BON and QGP, which is also supported by their higher physiologic levels of SSTR2 and SSTR5." (PMID 36555512, 2022). "Other reasons for the absence of a significant effect of SST analogues on tumor progression and survival could be resistance to SST analogues, including desensitization of the receptor or the presence of a spliced SSTR5 variant." (PMID 31569719, 2019). "However, a correlation of SSTR5 expression with tumor recurrence or regrowth was not seen." (PMID 34601710, 2022). "Within the 18 tumour specimens, SSTR2A showed the highest immunoreactivity with a median IRS of 8, while SSTR1, SSTR2B und SSTR5 had a median IRS of 3 and SSTR3 und SSTR4 showed no immunoreactivity (median IRS = 0)." (PMID 37707754, 2023). "SSTR2 expression, SSTR5 expression, and the SSTR2/5 ratio did not correlate with the tumor volume change rate following SSA treatment." (PMID 36435867, 2022). "Tumors were divided into two groups according to aggressiveness, the non-aggressive group (n = 19) had higher SSTR5 and SSTR1 expression than the aggressive (n = 16) tumor group." (PMID 35008325, 2021).
tumor (continued). "Among them, the expression of CNR2, GIP, GNGT1, NPY1R, SSTR5, and LEP in tumor tissue was significantly lower than in normal tissue, while the expression of GPSM2, and NMU was significantly highly expressed in tumor tissue." (PMID 33169793, 2020). "NMU was highly expressed in both tumor tissue and normal tissue, and NPY1R and SSTR5 were not collected in the HPA database." (PMID 33169793, 2020). "The HT29 cells, which were originally derived from a low grade, well-differentiated tumor, expressed SST and all five of its receptors, but the SW480 cells, which were originally derived from a high grade undifferentiated tumor, did not express SST or SSTR5." (PMID 27927191, 2016).
cancer (13 papers, 2013 to 2024). A tumor composed of atypical neoplastic, often pleomorphic cells that invade other tissues. "Using RT-PCR, studies have suggested the expression of SSTR1, -2 and -5 in most carcinomas with SSTR5 as a major receptor subtype at the mRNA level, similar to the protein expression levels." (PMID 38203605, 2023). "FAM159B co-localised with RGS9, D2R, SSTR4, and SSTR5 in the four cancer cell lines to a different extent." (PMID 36362289, 2022). "The expression of SST, SSTR2, SSTR3 and SSTR5 mRNA in the normal and cancer groups was detected using RT-PCR." (PMID 24260078, 2013). "Identification of PDX-1 as a transcriptional target for SSTR5 may help in guiding the choice of therapeutic cancer treatments." (PMID 25009500, 2014).
adenocarcinoma (2 papers, 2012 to 2024). A common cancer characterized by the presence of malignant glandular cells. "Among the patients with adenocarcinoma, the majority expressed low amounts of SSTRs; one patient had none, a few had moderate amounts, and only one patient expressed high amount of SSTR5." (PMID 22550583, 2012). "In this study, we investigated whether there was any correlation between the concentration of somatostatin receptors SSTR2A, SSTR2B, SSTR3, and SSTR5 in squamous cell carcinoma (SCC) and adenocarcinoma (Ac) compared to patients with Barrett's oesophagus without cancer." (PMID 22550583, 2012).
colonitis (1 paper, 2019). "It has been found that octreotide can stimulate NHE8 expression in colonitis mice, and somatostatin receptor 2 (SSTR2) agonist fragments and somatostatin receptor 5 (SSTR5) agonists can inhibit ERK1 / 2 phosphorylation by restoring NHE8 expression." (PMID 31139644, 2019).
SSTR5 also shares sentences with these, for which no sentence is quoted: gastric cancer (4 papers); somatotroph adenomas (4); gastroenteropancreatic neuroendocrine tumors (3); pheochromocytoma (3); colon carcinoma (2); Crohn disease (2); autism (1); benign tumours (1); bipolar disorder (1); cardiac arrhythmia (1); colon adenocarcinoma (1); Cushing syndrome (1); depression (1); endocervical carcinoma (1); epilepsy (1); Glucose intolerance (1); gonadotroph adenomas (1); head and neck squamous cell carcinoma (1); Head and neck tumor (1); hepatoblastoma (1); hepatorenal syndrome (1); hereditary spherocytosis (1); Hodgkins lymphoma (1); Hyperinsulinemia (1); intracranial meningioma (1); lung adenocarcinoma (1); lung carcinoma (1); malignant meningioma (1); medulloblastoma (1); meningothelial tumors (1).
A further 12 diseases each share a sentence with SSTR5 in 1 paper.